TNF (tumor necrosis factor)
Diseases named in the same sentence as TNF in open-access papers (continued):
Sharing a sentence is not in itself a finding about the gene and the disease.
tumor (continued). "More recently, the potential of agents, such as birinapant, that lower the tumour TNF cytotoxicity threshold and augment responses to immunotherapy has been demonstrated." (PMID 31947615, 2020). "Third, TNF/Mel/SM‐induced cell death appears to be more immunogenic, as cancer cells that die in this way more efficiently induce anti‐tumour immunity." (PMID 32419365, 2020). "TNF-α is produced by many different cell types, including macrophages, T lymphocytes as well as natural killer (NK), stromal and tumor cells." (PMID 33202705, 2020). "In this result, a variety of tumor-related signals were presented, such as regulation of autophagy, apoptosis, regulation of protein localization to membrane, cytokine activity, tumor necrosis factor, and ubiquitin protein ligase." (PMID 33133307, 2020). "We confirmed that CM from PCa cell lines induce anergy in healthy donor derived NK cells, with reduced capability to produce the anti-tumour cytokines IFNγ, TNFα and the cytotoxic factor granzyme-B." (PMID 33569050, 2020). "TNFα blockade increases the infiltration of tumor-specific CTLs, reduces the proliferation of immunosuppressive, regulatory T cells (Tregs) and minimizes toxicity of immune checkpoint blockade." (PMID 32733461, 2020). "TIM-3 was established as a negative regulator of T cell anti-tumor responses due to its association with an exhausted T cell state marked by the progressive loss of these cells’ ability to express IFN-γ, TNF-α and IL-2." (PMID 32858904, 2020). "Since the 1980s, studies have shown that transmembrane TNFα expressed on human macrophages and lymphocytes induces strong and long-term tumor regression." (PMID 33396603, 2020). "The use of cisplatin chemotherapy has been shown to increase tumor immune infiltration and tumor cell killing by tumor necrosis factor alpha (TNFα)-producing T cells." (PMID 33425717, 2020). "LY3039478 significantly enhanced IFN-γ+CD8+, Granzyme B+CD8+, and TNF-α+CD8+ T-cell proportions from tumour tissues compared with a control group." (PMID 32778818, 2020). "Previous study has showed that VEGF, TNF-α, IL-1β and MMPs derived from TAMs involve in tumor angiogenesis." (PMID 33201893, 2020). "Initially, as the tumor microenvironment in PDAC is inflammatory in nature, tumor cells secrete pro-inflammatory factors, such as TNF-α and IL-12, that recruit an influx of PMNs into the tumor site." (PMID 33022971, 2020). "Even though TNF/Mel/SM treatment significantly prolonged survival in this highly aggressive model, tumour‐bearing animals still eventually reached the tumour growth endpoint (Fig EV3B–E)." (PMID 32419365, 2020). "For example, upon contact with tumor cells, macrophages become activated, thus releasing inflammatory cytokines and chemokines such as TNF, IL-1, IL-6, IL-8, and IL-12." (PMID 32784928, 2020). "Classical activation of M1 macrophages in response to IFN-γ is characterized by a high ability to express antigens, high expressions of iNOS, IL-6, TNF-α, IL-1β mRNA, and nitric oxide (NO), which can kill endogenous pathogens and tumor cells." (PMID 33240950, 2020). "Depending upon the TME, TAMs are either transformed to inflammatory TAMs which suppress tumor growth by producing cytokines such as IL-12 and TNF or become anti-inflammatory to support tumor growth by producing TGF-beta, IL-10, and arginase." (PMID 33281826, 2020). "TNF-α is mainly expressed by Th1 and NK cells that can kill tumor cells and also attack trophoblast cells and embryonic tissues." (PMID 32775426, 2020). "On the hand recent studies showed that instead of augmenting effect of TNFα in tumor, TNFα blockade increases effect of immune checkpoint inhibitors." (PMID 32219066, 2020). "Pro-angiogenic factors in tumors induce down-regulation of adhesion molecules on endothelial cells in the tumor vasculature and induce anergy to inflammatory signals such as TNFα and IL-1." (PMID 31690961, 2020).
tumor (continued). "Neutrophils can promote tumor invasion, metastasis, and angiogenesis by producing various cytokines, such as tumor necrosis factor-alpha, vascular endothelial growth factor, fibroblast growth factor, angiopoietin, and interleukin." (PMID 33376559, 2020). "CXCL1, CXCL2, and CXCL5 have been shown to recruit MDSCs to the pre-metastatic niche through the interaction with CXCR2; once in the pre-metastatic site, MDSCs favor tumor cell recruitment and seeding by secreting TNFα, TGFβ, IL-6, CCL2 and CXCL2." (PMID 32823961, 2020). "In summary, our results support the notion in humans that some virus-reactive and tumor-infiltrating CD8 T cells undergo AICD in a TNF-dependent fashion." (PMID 32292509, 2020). "To validate that the deficiency in IFNγ synthesis driven largely by the CpG hypermethylation of the IFNγ promoter and not a general T cell defect, we used the same approach to assess the TNFα kinetics for each tumor-specific CTL clone." (PMID 32194559, 2020). "M1 macrophages secrete inflammatory factors including TNF-α and IL-12, and typically suppress tumor development." (PMID 32850356, 2020). "In line with the growing success of immunotherapy, triggering the TNF-induced Immunogenic Cell Death (ICD) of tumour cells is pursued with the view to enhancing Immune Checkpoint Inhibitor (ICI) efficiency." (PMID 32365592, 2020). "AcTakines were generated by fusing an inactivated TNF or IFN‐γ mutein with a tumor vasculature‐targeting CD13 VHH (resulting in CD13‐AFR and CD13‐AFN‐II, respectively)." (PMID 31912630, 2020). "TIE-2 expressing monocytes (TEM) are recruited to the tumor site where they have been shown to be essential for angiogenesis and inhibition of tumor cell apoptosis by mechanisms depending on TNF-α release." (PMID 33108409, 2020). "The frequencies of TNFα-producing cells seem to be restored after tumor resection, excepting classical monocyte subsets that displayed a significant decrease in TNFα production in HCC patients at T1." (PMID 32256215, 2020). "The first applied cytokine for immunotherapy of cancer was TNF-α, but accompany with its ability for inhibition of tumor progression, systemic administration of TNF-α led to severe toxicity." (PMID 32742605, 2020). "The immunohistochemical expression of TNF-α was increased in tumor groups with high proliferation rates (Ki-67; p = 0.034), as well as in those with higher tumor grades (p = 0.05)." (PMID 32156252, 2020). "In a study of a cohort of patients with inflammatory breast cancer it was found that there was a direct correlation between TNF-α production by peripheral blood T lymphocytes and the detection of circulating tumor cells expressing EMT markers." (PMID 32391269, 2020). "This suggests that other cytokines can be at play but that TNF-α levels determine how the balance of the tumor-promoting and –limiting contributions of these cytokines add up." (PMID 33267818, 2020). "These transcription factors were modulated to produce several important tumor growth-promoting cytokines, including TNF-a, IL- 1β, and IL-6." (PMID 32716955, 2020). "The anti-tumor activity of LCCs is manifested in two aspects: in vitro cytotoxicity and endogenous TNF production." (PMID 35498870, 2020). "It seems not even necessary to overactivate local endothelial cells, as shown by the application of a modified TNFα cytokine that upregulates adhesion molecules, but then even eradicates solid tumors through rapid destruction of the tumor neovasculature." (PMID 33343570, 2020). "TNF-α can act as a tumor suppressor through vascular destruction, tumor necrosis, and immunostimulation." (PMID 33029495, 2020).
tumor (continued). "Immature DCs stimulated by tumor antigen is activated to induce synthesis of cells and secretion of cytokines including interleukin-2 (IL-2), Tumor necrosis factor-α (TNF-α), interferon-β (IFN-β)." (PMID 33324558, 2020). "Hyperactivated STAT3 in tumor cells can suppress the expression of IL-12 and TNF-α, leading to a decrease in Bcl-2 expression in DCs." (PMID 32972405, 2020). "In this model, tumor volumes in mice given entolimod before TNF/D-GalN initially decreased slightly with subsequent growth being much slower than in mice that were untreated, injected with D-GalN only or injected with D-GalN after entolimod." (PMID 32027657, 2020). "In the case of TNF, we must be careful to avoid tipping the delicate balance of TNF signaling from apoptotic to proliferative due to intrinsic factors in the tumor microenvironment." (PMID 31130731, 2020). "We recently identified that intratumoral PD-1+Lag3+Tox+ exhausted tumor antigen-specific T cells not only lose functionality (e.g., IFNγ, TNFα), they progressively express IL-10 specifically in the TME." (PMID 33584701, 2020). "PD-L1-CAR T cells also demonstrated antigen-specific production of cytokines IL-2, IFN-γ, and TNF-α when incubated with PD-L1high tumor cell lines HCC827 and H1975 in vitro." (PMID 32792499, 2020). "The different TNF-α isoforms can have different effects on inflammatory responses and tumor development." (PMID 32592356, 2020). "To further evaluate crosstalk between Trichomicin and the tumor microenvironment in vitro, we investigated the ability of Trichomicin to reduce the expression and secretion of IL-6 and TNFα in macrophage-like differentiated THP1 cells." (PMID 32317968, 2020). "One anti-tumor strategy would consist of switching the roles of TNFα, FasL and TRAIL from their pro-apoptotic functions to favor tumor cell death." (PMID 32370259, 2020). "Conversely, antigen-specific CD8+ T cells use TNF-α as part of their anti-tumor effector arsenal to better support the antibody-dependent cell-mediated cytotoxicity (ADCC) driven by trastuzumab." (PMID 32013102, 2020). "This is in accordance with the work of Johansson and colleagues showing that tumor vasculature‐targeted TNF (via an RGR peptide) improved tumor vessel function and reduced leakiness in a Rip1‐Tag5 pancreatic tumor model." (PMID 31912630, 2020). "It is triggered by the activation and expansion of the CAR T-cells and lysis of normal and tumor cells, leading to the release of effector cytokines such as IL-2, tumor necrosis factor-α (TNF-α) and interferon-γ (IFN-γ)." (PMID 32850376, 2020). "The ability of a tumor to produce and respond to TNF (or another TNFSF death ligand) is vital for the anti-tumor effect of SMs, and tumors that lack either of these functions will most likely be resistant to SM treatment." (PMID 32053868, 2020). "Another limitation of our study is that no in vivo experiments were performed to determine the contributions of M0 macrophages to tumor growth and the effects of TNF-α inhibition in such a setting." (PMID 33267818, 2020). "Activated NK cells secrete large amounts of IFN-γ, granulocyte-macrophage colony-stimulating factor, TNF-α, IL-18, and other factors to inhibit tumor growth." (PMID 32993787, 2020). "For example, in DMBA (7,12-dimethyl-benz(a)anthracene)-induced skin carcinogenesis, increased tumor progression correlated with elevated TNF-α levels." (PMID 33202705, 2020). "High loco-regional doses of TNF-α have been shown to induce hemorrhagic necrosis via selective destruction of tumor blood vessels and generation of specific T cell antitumor immunity." (PMID 32636744, 2020). "Although in vitro/in vivo and preclinical TRAIL-based therapies demonstrated encouraging results and low toxicity owing to tumor-specific activity, the use of death receptors, such as FasL or TNF, as anticancer therapy was soon dampened." (PMID 32466293, 2020).
tumor (continued). "The highest TNF-α level in tumor tissues of the siRNA2@HPVP group demonstrated the superior immunogenic effect of siRNA2@HPVP than HPVP and siRNA2." (PMID 32332752, 2020). "In fact, many studies have shown that various cytokines such as tumor TNF-α and IL-6 are involved in the pathogenesis of CHD." (PMID 32508942, 2020). "* Myeloid cells were connected to tumor recurrence following surgery and to exitfrom dormancy.* Myeloid cells acted in this respect via soluble mediators like TNFα, IL-1β and VEGF-A,and through COX enzymes." (PMID 33585241, 2020). "In a clinical trial approved by the FDA, whose first phase has been completed, novel PEGylated AuNPs were utilized to deliver TNF into cancer cells, ending with selective TNF storage in tumor cells." (PMID 32806755, 2020). "Expression of TNF-alpha and IL-2 attracts T cells to the tumor and also enhances their infiltration into the cancer cells." (PMID 33053757, 2020). "Accordingly, TAMs secrete a series of specific pro-angiogenic factors (VEGF, IL-1β, TNF-α, angiogenin and semaphorin 4D) promoting an angiogenic switch and neovascularization together with a more malignant transition of the tumor cells." (PMID 32751163, 2020). "Conversely, TNF-α in the tumor microenvironment can differentially modulate radiosensitivity through a variety of signaling mechanisms." (PMID 32527042, 2020). "During a CAR T cell attack through released IFN-γ and TNF-α, the MSCs shift towards a more acute inflammatory response resulting in an improved anti-tumor reactivity and persistence of CAR T cells." (PMID 32260097, 2020). "Higher levels of IFN-γ and TNF-α production by NK cells, and greater cell lysis, were found for the tumor cells with higher CD38 receptor density (>100,000 molecules/cell vs. <100,000 molecules/cell)." (PMID 32922390, 2020). "Mast cell- and macrophage-derived growth factors that can promote tumor development and angiogenesis include TNF-α, TGF-β1, FGF-2, VEGF, platelet-derived growth factor (PDGF), IL-8, osteopontin, and nerve growth factor (NGF)." (PMID 32508920, 2020). "In contrast to the presence of infiltrating F4/80-positive macrophages and the elevated expression of F4/80 and Ly6c, the mRNA expression of TNFα, IL-6, Il-1β, and IL-17 were paradoxically downregulated in the tumor-bearing 12-month-old Atg7ΔHep livers." (PMID 32382012, 2020). "Hartley and colleagues showed that versican produced by mouse tumor cells stimulated monocytes to produce TNFα in a TLR2-dependent manner which in turn upregulated the expression of PD-L1 by mouse monocyte/macrophages." (PMID 32265939, 2020). "M1 macrophages play an anti‐tumour role by activating the immune system and producing reactive oxygen species, nitric oxide and TNF." (PMID 31642585, 2020). "Strikingly, while tumor‐infiltrating cDC2s and pDCs were defective in response to TLR‐L stimulation, TNFα and IFNλ1 production by tumor‐infiltrating cDC1s remained similar to HD." (PMID 33282290, 2020). "Since Birinapant sensitizes cells to TNF receptor-induced apoptosis, we also co-treated the cells with TNFα, mimicking a pro-inflammatory tumor microenvironment (TME)." (PMID 33257690, 2020). "This trend is also consistent with the IL-6 levels measured in the tumor mass, however, the differences of TNF-α level in the tumor mass between mouse groups receiving 2 and 8 Gy irradiation are marginal." (PMID 32541769, 2020). "To this end, we measured the expression levels of IFN-γ and TNF-α, representative antitumor effector cytokines, 33 in splenic and tumor-infiltrating T cells in WT and Lsp1 KO mice by flow cytometry." (PMID 33020243, 2020). "We co-cultured TILs and autologous tumor cell lines for five hours in the presence of Golgi-Plug and measured the expression of CD107a and the intracellular accumulation of TNF and IFN-γ." (PMID 32127601, 2020).
tumor (continued). "PMA is a potent tumor inducer that can facilitate the activation of TNF-α, NF-κB and AP1 (activator protein 1) and has been shown to induce a Th2 lymphocyte cell response." (PMID 32796864, 2020). "IL-6 and TNF-α, two critical inflammatory mediators involved in the stimulation of tumor microenvironment, were measured in both serum and colon extracts." (PMID 32664279, 2020). "First, iNKT cells can produce an abundant amount of Th-1 type cytokines such as IFNγ and TNFα, which can promote an inflamed immune-microenvironment beneficial for anti-microbial or anti-tumor immunity." (PMID 33329531, 2020). "Inflammation is a key factor in inducing tumor development, and cytokines, such as TNF involved in chronic inflammation contributed to this microenvironment." (PMID 32171282, 2020). "Detection of IL-6, TNF-α, and TGF-β in blood of tumor-bearing nude mice showed that C-PC/CMC-CD55sp nanospheres induced an immune response that was associated with tumor growth inhibition." (PMID 32636744, 2020). "A decreased secretion of IFN-α, TNF-α, and IL-6 by tumor infiltrating pDCs was also detected in OSCC." (PMID 32054102, 2020). "In general, CAR-T cells would kill tumor cells accompanied with the release of cytokines, including IL-2, IL-4, IL-6, IFNγ, and TNFα." (PMID 31998790, 2020). "Compared to the control group, the content of anti-tumor immunity-related cytokines IFN-γ, TNF-a, IL-2, and IL-5 increased, while IL-6, related to inhibiting anti-tumor immunity, decreased in the TME." (PMID 32802195, 2020). "The direct stimulation of macrophages with BCG can also elicit high levels of TNF-α that can result in direct tumor cell kill." (PMID 32858811, 2020). "It was previously reported that paramylon stimulated tumor TNFα in murine J774 macrophage cells, although the mechanisms were not further investigated." (PMID 32560675, 2020). "Sera of mice bearing A20 tumours were sampled at 120-h post treatment for analysis of cytokines, including IL-6, TNF-α and IFN-γ." (PMID 33014356, 2020). "For aPD-L1 + PDT + PTT group, tumor presented the highest level of IL-12, TNF-α, and IFN-γ, owing to the capability of IL-12 to induce the secretion of IFN-γ." (PMID 32620811, 2020). "LTB (lymphotoxin β) is a tumor necrosis factor (TNF)-related cytokine that initiates extrinsic apoptotic cell death in tumor cells via the LTβR signaling pathway." (PMID 32513298, 2020). "B10-(CD3xJB8) showed cytotoxicity against HLA-A24(+)/DNAJB8(+) tumour cells; however, the frequencies of IL-2 and IFNγ-secreting cells were lower than those of TNFα." (PMID 32753678, 2020). "Recent studies have suggested that TNF-α can exert both anti-angiogenic and pro-angiogenic effects in different tumor tissues, likely due to differences in its expression." (PMID 32993787, 2020). "They promote angiogenesis via VEGF, promote tumor development and metastasis through cathepsin G and ROS, induce chronic inflammation by releasing TNF-α, IL-1β, IL-6, and IL-12, and inhibit effector CD8+ T cells." (PMID 32499786, 2020). "CCR6 signaling also promotes murine transplantable colon cancer by recruiting macrophages to the TME through a CCL2-CCR6 axis, which results in the release of IL-1β, IL-6, and TNFα, further enhancing tumor progression." (PMID 32733461, 2020). "In the BNL tumor model, combining the same TNF/D-GalN treatment with entolimod pretreatment 1 h prior resulted in both mouse survival and significant suppression of tumor growth." (PMID 32027657, 2020). "In contrast, intratumoral TAMs distinctly showed immunosuppressive function from the early stage of the tumor via TNF-α." (PMID 32518979, 2020). "The main experimental challenge in this situation would be to achieve “pure” necroptosis via physiological necroptosis inducers (i.e., cytokines like TNF or IFNs) in an in vivo tumour setting." (PMID 32752206, 2020).